PLXNB1 (plexin B1)
Diseases named in the same sentence as PLXNB1 in open-access papers (continued):
Sharing a sentence is not in itself a finding about the gene and the disease.
cystadenocarcinoma (1 paper, 2010). A malignant cystic epithelial neoplasm arising from the glandular epithelium. "Plexin-B1 immunoreactivity was present in 3 (15.00%) normal and benign ovarian samples, in 7 (35.00%) borderline tumors and in 44 (55.00%) cystadenocarcinomas." (PMID 21059203, 2010). "In borderline tumors, the expression levels of Plexin-B1 were neither significantly higher nor significantly lower than the levels in the normal and benign tissues or the cystadenocarcinomas." (PMID 21059203, 2010).
eosinophilia (1 paper, 2023). "Namely, Plexin B1 deficiency leads to increases in BALF and lung tissue inflammation, eosinophilia, mucus production, and Th2 cytokines in BALF, but downregulates IL-10." (PMID 38259471, 2023). "Plexin B1-deficiency in mice also led to an upregulation of these and additional features of allergic inflammation in the OVA/Alum model including eosinophilia, mucus score and mucous cell hyperplasia, and lung local Th2 cytokine production." (PMID 38259471, 2023).
Infertility (1 paper, 2017). "We evaluated expression of β3 integrin, calcitonin and plexin-B1 through mRNA level measurement with real-time RT-PCR, in the endometrium of 16 infertile women with unexplained infertility and 10 fertile women." (PMID 28280798, 2017). "A significant correlation was observed between calcitonin and plexin-B1 mRNA expression levels only in patients with unexplained infertility (r=0.580; p=0.001)." (PMID 28280798, 2017). "There were significant correlations between expression of β3 integrin with calcitonin and plexin-B1 in fertile and infertile women." (PMID 28280798, 2017). "Also, there was a significant correlation between β3 integrin and plexin-B1 mRNA expression levels in the healthy fertile control group (r=0.647; p=0.002) and in infertile women (r=0.706; p<0.01)." (PMID 28280798, 2017). "Furthermore, in present study we found positive correlations between β3 integrin, calcitonin and plexin-B1 expression at the window of implantation in both fertile and infertile women." (PMID 28280798, 2017). "Thus, present study was undertaken to investigate whether β3 integrin, calcitonin and plexin-B1 expression alter at the window of implantation in endometrium of infertile patients with unexplained infertility." (PMID 28280798, 2017). "Moreover, in present study levels of plexin-B1 expression in the window of implantation was lower in infertile women but the difference was not statistically significant." (PMID 28280798, 2017).
ovarian adenocarcinoma (1 paper, 2010). An adenocarcinoma that arises from the ovary. "Plexin-B1 expression was found in 7/11 ovarian serous adenocarcinomas, and 6/15 ovarian adenocarcinomas expressed both Met and Plexin-B1, which was predictive of an unfavorable outcome." (PMID 21059203, 2010).
ovarian serous adenocarcinoma (1 paper, 2010). An adenocarcinoma that arises from the ovary and is characterized by the presence of malignant epithelial cells that, in well differentiated tumors, resemble the epithelium of the fallopian tube or, in poorly differentiated tumors, show anaplastic features and marked nuclear atypia. "Plexin-B1 was strongly expressed in tissues of patients with ovarian serous adenocarcinomas and its expression was found to be associated with lymph node metastasis." (PMID 21059203, 2010).
ovarian serous tumor (1 paper, 2010). A benign, borderline, or malignant epithelial tumor of the ovary characterized by the presence of neoplastic epithelial cells that, in well differentiated tumors, resemble the epithelial cells of the fallopian tube and, in poorly differentiated tumors, show anaplastic features. "Additional studies are warranted to elucidate the role of Plexin-B1 as a possible tumor marker as well as a putative therapeutic target for ovarian serous tumors." (PMID 21059203, 2010). "In the present study, immunohistochemical analysis was used to investigate Plexin-B1 expression in ovarian serous tumors in a larger series." (PMID 21059203, 2010). "Plexin-B1 expression correlates with malignant phenotypes of serous ovarian tumors, probably via phosphorylation of AKT at Ser473, suggesting that Plexin-B1 might be a useful biomarker and/or a novel therapeutic target." (PMID 21059203, 2010).
ovarian tumors (1 paper, 2010). "In the present study, Plexin-B1 expression was explored in benign and malignant human ovarian tumor tissues." (PMID 21059203, 2010). "However, whether or not Plexin-B1 expression is involved in human ovarian tumors remains unclear." (PMID 21059203, 2010).
pheochromocytoma-paraganglioma (1 paper, 2020). A rare neuroendocrine tumor arising from chromaffin cells of the adrenal medulla (pheochromocytoma) or from sympathetic and parasympathetic ganglia (paraganglioma). "In pheochromocytoma & paraganglioma (PCPG), PLXND1 was negatively, while PLXNB1 and B3 were positively correlated with both RNAss and DNAss." (PMID 32640719, 2020).
postmenopausal osteoporosis (1 paper, 2022). Metabolic disorder associated with fractures of the femoral neck, vertebrae, and distal forearm. "Indeed, our study reveals that the anti–Plexin-B1 antibody RbPLX7 exerts beneficial effects in a mouse model of postmenopausal osteoporosis." (PMID 35850304, 2022).
primary effusion lymphoma (1 paper, 2019). A large B-cell lymphoma located in the body cavities, characterized by pleural, peritoneal, and pericardial fluid lymphomatous effusions and that is always associated with human herpes virus-8 (HHV-8). "The HGF/c-MET pathway appears further largely activated in malignant cells from primary effusion lymphoma (PEL): here the expression of plexin B1 is required for c-MET-mediated survival of PEL cells." (PMID 30642077, 2019).
progressive multifocal leukoencephalopathy (1 paper, 2022). Progressive multifocal leukoencephalopathy (PML) is a neurological disorder that damages the myelin that covers and protects nerves in the white matter of the brain. "Given that Plexin-B1 is expressed on microglia, rather than on lymphocytes, it seems reasonable to assume that a therapy based on Plexin-B1 blockade is not expected to carry the risk of progressive multifocal leukoencephalopathy." (PMID 35850304, 2022).
Sciatica (1 paper, 2021). Pain in the lower back and hip radiating in the distribution of the sciatic nerve. "AZU1, BPI, TCF7L2, and WFIKKN1 were upregulated in sciatica patients, while ANGPTL4, CRP, EREG, FAM19A4, FGF1, LOC100129216, PLXNB1, RLN1, and RXFP2 were downregulated." (PMID 34925462, 2021).
serous ovarian cystadenocarcinomas (1 paper, 2010). "The expression of Plexin-B1 in serous ovarian cystadenocarcinomas was statistically higher than that in the normal and benign tissues." (PMID 21059203, 2010).
skin cancer (1 paper, 2021). "In summary, these data indicate that Plexin-B1/Plexin-B2 limit YAP activity and proliferative capacity not only during embryonic development but also in skin cancer in mice." (PMID 33637728, 2021).
skin tumors (1 paper, 2021). "To assess the potential pathophysiological relevance of mechanosensation through Plexin-B1/Plexin-B2 in disease, we next analyzed the role of Plexin-B1/Plexin-B2 in skin tumors." (PMID 33637728, 2021).
tumor (56 papers, 2007 to 2025). "Sema4D/Plexin B1 interaction participated in angiogenesis, regulating tumor-associated macrophages, and control of invasive growth." (PMID 32382577, 2020). "PLXNA4 and PLXNB1 had significantly increased expression in subtype C5, suggesting an association between higher gene expression and favorable immune infiltrate type, indicating a tumor suppressor role." (PMID 32640719, 2020). "Furthermore, recent studies have shown that loss of Plexin-B1 expression in breast cancer correlates closely with ER status and indicates a more aggressive tumor phenotype." (PMID 21059203, 2010). "Signaling via Plexin B1 activates cell migration of neuronal, epithelial, and tumor cells, including angiogenesis." (PMID 38439958, 2024). "The soluble cleaved form of sema4D was found to promote epithelial-mesenchymal transition (EMT) and, consequently, tumor cells metastasis via plexin-B1." (PMID 37627074, 2023). "As a ligand of Plexin-B1, Sema4D plays important roles in tumor cell proliferation, survival, and migration." (PMID 37096066, 2023). "Plexin B1 was shown to play a redundant role during mouse neuronal development and in tumour angiogenesis likely due to functional overlap with other Plexin family members." (PMID 38259471, 2023). "In contrast, overexpression of WT Plexin-B1 in prostate epithelial cells of Ptenfl/flKrasG12V mice suppressed tumor cell invasion into the stroma (P < 0.05)." (PMID 36936664, 2023). "Plexin-B1 is expressed by endothelial cells in the tumor microenvironment in addition to tumor epithelial cells." (PMID 36936664, 2023). "Sema4D and its receptor, Plexin-B1, play crucial roles in the process of immune regulation, angiogenesis, and tumor progression." (PMID 37096066, 2023). "To establish the stage at which stage Plexin-B1 expression affects metastasis, we investigated the effect of expression of the different forms of Plexin-B1 on invasion of primary tumor cells into the prostate stroma." (PMID 36936664, 2023). "Plexin-B1 was also found to function as a tumor suppressor gene in primary melanoma harboring an activated Raf oncogene." (PMID 37627074, 2023). "CD100 is highly expressed by tumor-associated macrophage (TAM) and interactions with plexin B1 within the TME promote tumor angiogenesis." (PMID 35480230, 2022). "Since c-Met is one of the most commonly deregulated oncogene in cancers, its collaboration with Sema4D/Plexin-B1 is an alternative pathway to promote tumor invasion." (PMID 29971044, 2018). "Plexin-B1 combines with SEMA4D secreted into the microenvironment from tumor cells to promote tumor angiogenesis and endothelial cell migration and vessel formation." (PMID 29308068, 2018). "The Sema4D-Plexin B1 expression was found to be significantly related to tumor’s stage, depth of tumor invasion, lymph node metastasis, lymphatic invasion, and venous invasion, but unrelated to the patient’s age and gender." (PMID 30134791, 2018). "To investigate if Sema4D mediates TGF-β1 production, through binding to its receptor Plexin-B1 on tumor cells, we used siRNA system for transient silencing of Plexin-B1 in several HNSCC cell lines of the oral tongue." (PMID 29541402, 2018). "We summarize the role of Sema4D/Plexin-B1 in cancers based on overexpression of Sema4D or Plexin-B1 by the cancer cells or by other cells in the tumor microenvironment including immune cells, and the role of Sema4D/Plexin-B1 in distant metastasis." (PMID 29971044, 2018). "Sema4D and its receptor Plexin-B1 are commonly dysregulated in cancers, suggesting roles in cancer progression, invasion, tumor angiogenesis, and skeletal metastasis." (PMID 29971044, 2018). "Interaction of Sema4D-expressing CD5+ B-cells or leukemic-B-cells with Plexin-B1-expressing cells led to improved tumor survival." (PMID 28003812, 2016). "ErbB-2-overexpressing tumours depend on Plexin-B1-mediated RhoA activation for tumour progression and metastasis." (PMID 25137062, 2014).
tumor (continued). "Conversely, an important role of the SEMA4D-Plexin-B1 interaction in regulating different aspects of tumor progression and angiogenesis is well established." (PMID 25193853, 2014). "In endothelial cells, activation of Plexin-B1 induces a pro-angiogenic response in a RhoA-dependent manner, which is of particular importance for the neovascularization of tumours." (PMID 25137062, 2014). "Subsequent studies show that Sema4D participates in axon guidance, angiogenesis and tumor progression, and that these events are mediated by a high affinity receptor, plexin B1, and possibly plexin B2." (PMID 23741311, 2013). "Conversely, PLXNB1 has been shown to be expressed on the surface of tumor cells, but less so on neighboring endothelial cells." (PMID 23667446, 2013). "Similar findings were reported in human pancreas, where Sema4D-positive infiltrating lymphocytes interacted with plexin B1-positive tumor cells in pancreatic ducts." (PMID 23741311, 2013). "In contrast to these oncogenic roles of Sema4D, however, various lines of evidence point to a tumor suppressor role of its receptor plexin-B1." (PMID 23050142, 2012). "Cumulative evidence regarding the roles of Sema4D- Plexin-B1 interaction in tumor progression came from in vitro and in vivo studies." (PMID 20858260, 2010). "Here, we critically review and delineate the Sema4D-Plexin-B1 interaction in many facets of tumor progression: tumor angiogenesis, regulation of tumor-associated macrophages and control of invasive growth." (PMID 20858260, 2010). "The mechanistic roles of Sema4D and Plexin-B1 in the tumor microenviroment such as tumor angiogenesis, regulation of tumor-associated macrophages as well as the invasiveness of the tumor itself are highlighted in the following discussion." (PMID 20858260, 2010). "Similar to other in vitro studies, tumor angiogenesis induction by Sema4D is mediated through its interaction with Plexin-B1." (PMID 20858260, 2010). "By competing for Plexin-B1, these two molecules counter each other's effects in the same tumor cell, determining the net antimigratory or promigratory effect of Sema4D." (PMID 20858260, 2010). "Via interaction with its high affinity receptor Plexin-B1, Sema4D-Plexin-B1 involvement in tumor progression is strongly implied." (PMID 20858260, 2010). "In vitro and in vivo studies recently have given many insights into the involvement of Sema4D in tumor progression via interaction with Plexin-B1." (PMID 20858260, 2010). "It is also well documented that Sema-4D, along with its receptor, Plexin-B1, participate in tumor growth and proliferation." (PMID 17376242, 2007). "The expression levels of PLXNB1 could be subject to a multitude of influences, such as the composition of the tumour microenvironment and crosstalk with other signalling pathways." (PMID 39443302, 2024). "Furthermore, PLXNB1P1597L significantly increased invasion of tumor cells into the prostate stroma, while PLXNB1WTreduced invasion, suggesting that Plexin-B1 has a role in the initial stages of metastasis." (PMID 36936664, 2023). "In addition, the Ptenfl/flKrasG12V line was crossed with PLXNB1WT mice to establish the effect of overexpression of WT Plexin-B1 on tumor progression." (PMID 36936664, 2023). "Normal levels of WT Plexin-B1 in tumor cells may promote metastasis while overexpression of PLXNB1WT reduces metastasis." (PMID 36936664, 2023). "Additionally, plexin-B1 and plexin-B2 were also found to function as tumor suppressors in basal cell carcinoma." (PMID 37627074, 2023). "Thus, interaction between Sema4D expressed in GBM cells and Plexin-B1-expressing NK cells seems to promote the NK-cell-mediated killing of tumor cells." (PMID 31052281, 2019). "In some cancers, however, Plexin-B1 acts as a tumor suppressor." (PMID 29971044, 2018).
tumor (continued). "Also binding of Sema4D to its high affinity receptor Plexin-B1, was shown to mediate downstream activation of RhoA and subsequent microtubule organization enhancing cellular motility and tumor invasion, correlating with poor prognosis." (PMID 29541402, 2018). "Sema4D is over expressed in HNSCC, prostate, colon, breast, lung, cervical and ovarian malignancies and it was described to induce tumor angiogenesis through binding to its high affinity receptor Plexin-B1 on endothelial cells promoting their proliferation and organization." (PMID 29541402, 2018). "In addition to direct proliferative actions in cancer cells, Sema4D/Plexin-B1 abnormalities within the tumor niche support cancer progression by promoting angiogenesis." (PMID 29971044, 2018). "In ErbB-2-overexpressing tumours, ErbB-2 signals through Plexin-B1 and RhoA to promote metastasis." (PMID 25137062, 2014). "Sema-4D is a cell surface membrane protein that is shed from tumor cells and promotes endothelial cell proliferation, migration, angiogenesis, and tumor invasive growth through its action on its cognate endothelial receptor, plexin B1." (PMID 24886166, 2014). "In addition, an important role of SEMA4D-Plexin-B1 interaction in regulating different aspects leading to tumor progression, including invasive growth and angiogenesis, is well established." (PMID 25193853, 2014). "Thus, differences in expression of NRP1 and NRP2 measured by microarray can be assumed to be primarily due to endothelial cells, and differences in PLXNB1 due to tumor cells." (PMID 23667446, 2013). "As reviewed by Ch’ng and Kumanogoh, several studies have described a role for Sema4D and plexin-B1 in tumor progression, including soft tissue sarcomas, B-cell chronic lymphocytic leukemia, renal cell carcinoma, breast and ovarian carcinomas, prostate adenocarcinoma, and pancreatic cancer." (PMID 23741311, 2013). "Patterns of gene expression associated with the 2,656-tumor dataset were found in both TCGA datasets, including the low PC4a gene expression signature of high VEGFA and low SEMA3B, SEMA3C, SEMA3F, and PLXNB1." (PMID 23667446, 2013). "In vitro assays indicated that Plexin-B1 contributes to tumor migration and invasion." (PMID 21059203, 2010). "However, the role of the PLXNB1/SEMA4D axis in tumours has been elucidated by several studies." (PMID 39443302, 2024). "Consequently, WT Plexin-B1 activation inhibits tumor progression in mouse models of metastasis." (PMID 36936664, 2023). "Activation of Plexin-B1 on endothelial cells by Sema4D which is expressed by tumor cells, promotes angiogenesis; therefore, whole-body knockout of Plexin-B1 in our mouse models would inhibit Sema4D-induced angiogenesis and this may contribute to the decrease in metastasis observed." (PMID 36936664, 2023). "Sema4D/Plexin-B1 responses may vary among different cell lines of the same tumor type." (PMID 29971044, 2018). "Given that IKK activation enhances Plexin-B1-dependent activation of RhoA, which is known to subsequently increase the promigratory activity of cancer cells and to increase tumour progression, the IKK-complex may exert some of its tumour-promoting activity through enhanced plexin signalling." (PMID 25137062, 2014). "In contrast, SEMA3C is upregulated in cancers like prostate cancer and promotes tumor progression via EGFR, HER2, and MET activation through Plexin B1." (PMID 41009819, 2025). "Therapeutic strategies that restore SEMA3A/3F signaling or inhibit SEMA3C, such as semaphorin analogs, Plexin B1-Fc decoys, and anti-SEMA3C antibodies, have shown promise in reducing tumor growth and neural infiltration in preclinical cancer models." (PMID 41009819, 2025). "In summary, this study provides new insights into the role of the PLXNB1/SEMA4D axis in LM development of CRC, as well as providing a more comprehensive understanding of the immunological characteristics of tumour metastasis." (PMID 39443302, 2024).